CCT2 (chaperonin containing TCP1 subunit 2)
Diseases named in the same sentence as CCT2 in open-access papers (continued):
Sharing a sentence is not in itself a finding about the gene and the disease.
tumor (28 papers, 2004 to 2026). "Using univariate Cox regression analysis followed by multivariate Cox regression analysis, we built a risk score formula comprising prognostic HSPs (HSPA2, DNAJC20, HSP90AA1, CCT1, CCT2) and tumor stage to identify high-risk and low-risk cases." (PMID 31101846, 2019). "In addition, the expression of CCT2 is associated with histological grade, suggesting that it is associated with tumor differentiation and progression." (PMID 32117430, 2019). "Genetic depletion of CCT2 suppresses tumor cell proliferation and migration in vitro and inhibits tumor growth in vivo." (PMID 42003909, 2026). "On the basis of these collective data, we conclude that CCT2 is essential for tumor development, metastasis, and immune evasion." (PMID 39079960, 2024). "The levels of CCT2 in MBC by immunostaining tumor tissues were examined with 38 MBC patients, S4 Table." (PMID 35749519, 2022). "Further analysis in TCGA demonstrated that CCT2 was upregulated in tumor tissues compared with normal tissues and positively correlated with BCAT1 expression." (PMID 34164393, 2021). "For instance, in the Roessler Liver 2 dataset, CCT2 was overexpressed by 2.084-fold in HCC tissues compared to adjacent non-tumor tissues (p=1.33E-53)." (PMID 34676169, 2021). "CCT2 expression was significantly higher in tumor tissues compared with normal tissues (P < 0.0001), and this result was further validated in four independent microarray datasets derived from GEO database." (PMID 33869000, 2021). "CT20p thus demonstrates that CCT2 and the chaperonin complex can be therapeutically targeted and have biological outcomes such decreasing tumor growth." (PMID 33996588, 2021). "Both results from GPL570 and GPL96 microarray platforms revealed that global CCT2 expression was higher in tumor tissues compared with normal tissues." (PMID 33869000, 2021). "Inducible loss of CCT2 in tumor cells implanted in mice impaired tumor growth, indicating that CCT2 is essential for the in vivo replication of tumor cells." (PMID 31964905, 2020). "The role of TRiC in tumour aggression has been further corroborated by the successful implementation of cytotoxic peptides such as CT20p that reduce tumour burden by targeting CCT2." (PMID 32635403, 2020). "We found that the levels of STAT3 consistently correlated with CCT2 in most SCLC patient tumor tissues." (PMID 29299146, 2017). "The percentage of tumor samples with CCT2 expression detected by IHC was significantly different between large tumors and small tumors." (PMID 23782473, 2013). "The expression of CCT2 in tissue samples of SC/ASC significantly correlated with tumor size, TNM stage, and lymph node metastasis status." (PMID 23782473, 2013). "In conclusion, positive expression of CCT2 and PDIA3 are associated with large tumor size, high TMN stage, lymph node metastasis, adjacent tissue invasion, and poor prognosis of SC/ASC and AC." (PMID 23782473, 2013). "Increased expression of CCT2 also contributes to tumor cell resistance to chemotherapy and radiation therapy." (PMID 23782473, 2013). "65.4% of large tumors (tumor > 3 cm) had CCT2 expression whereas only 30% of small tumors (tumor ≤ 3 cm) showed CCT2 expression." (PMID 23782473, 2013). "Furthermore, co-culture and exosome treatment experiments reveal that CCT2 promotes M2 macrophage polarization and establishes an immunosuppressive tumor microenvironment through coordinated metabolic and exosome-mediated mechanisms." (PMID 42003909, 2026). "CCT2 was highly expressed in tumor tissues, which indicated a poor prognosis." (PMID 38166853, 2024). "This demonstrates that CCT2 as a biomarker could bring a unique solution to the problem of tumor heterogeneity." (PMID 35749519, 2022). "In the MBC study, all tumor tissue samples were positive for CCT2 staining." (PMID 35749519, 2022). "Hence, in this model, the inhibition of CCT2 prevented tumor growth through decreases in Gli-1 levels." (PMID 35602608, 2022).
tumor (continued). "The use of CCT2 for the detection of CTCs is supported by our data showing that CCT2 protein levels are increased in tumor tissues compared to normal tissues and may be a better marker for metastatic tissues than CK." (PMID 35749519, 2022). "While most CTC enrichment technologies focus on either physical or biological properties, staining for CCT2 to identify CTCs could have a wide application that is particularly beneficial for tumor heterogeneity." (PMID 35749519, 2022). "Early-stage IDC tumor samples also showed minimal to low CCT2 staining." (PMID 35749519, 2022). "CCT2 was higher in most of the tumor tissues when compared with normal tissues." (PMID 33869000, 2021). "Based on these observations, we concluded that CCT2 overexpression confers to tumor cells enhanced growth potential and adaptability, even as these cells transition between suspension and adherent culture conditions, suggestive of the potential for invasive and metastatic-like behavior." (PMID 33996588, 2021). "Tumor tissues were recovered from these mice for immunohistochemistry (IHC) analysis of CCT2." (PMID 31964905, 2020). "Among these genes, CDK4, CCT2, and MGAT1 were associated with overall survival and recurrence-free survival, and the expression levels of these three genes were significantly higher in tumor tissues." (PMID 32117430, 2019). "Moreover, 85.7% of stage IV tumor samples expressed CCT2, which was significantly higher than that of stage III (40%) and stage I+II (20%) tumor samples." (PMID 23782473, 2013). "In addition to its up-regulation in GBC, CCT2 up-regulation has been reported in other human tumors and is related to drug-resistance of tumor cells." (PMID 23782473, 2013). "For further analysis of melanotic tumor formation process, we focused our attention on 5 genes that induced melanotic mass to high frequency and might represent different classes of melanotic tumor suppressor genes: cct2, cul4, hyx, mRpS30 and ush." (PMID 20540764, 2010). "Flow cytometry analysis revealed a significant increase in the quantity of CD4+ T cells among all the immune cells analyzed in the 4T1-shCCT2 tumors but not in the number of CD8+ T cells, tumor-associated macrophages (TAMs), or myeloid-derived suppressor cells (MDSCs) upon CCT2 suppression." (PMID 39079960, 2024). "Moreover, CCT2 expression was found to be associated with tumor grade in METABRIC cohort, but not tumor size and ER status." (PMID 33869000, 2021). "Interestingly, among these HSPs, overexpression of HSPA2 and DNAJC20 was associated with better prognosis (tumor suppressor-like activity), whereas high expression of other heat shock genes (HSP90AA1, CCT1, CCT2 and CCT6A) correlated with poor survival (oncogene-like activity)." (PMID 31101846, 2019). "CCT2 and CCT5 are two additional proteins found to decrease in abundance with increasing tumor severity." (PMID 41441336, 2025). "CCT2 and CCT5 have been shown to promote tumor invasion and metastasis by stabilizing the cytoskeleton." (PMID 41168872, 2025). "Hsa_circ_001726 is derived from the parental gene CCT2, which has previously been reported to be highly expressed in HCC tumor tissues, correlating with unfavorable clinical outcomes for HCC patients." (PMID 38166853, 2024). "The results revealed that CCT2 expression in BRCA, PRAD, and THYM was significantly different from tumor grade." (PMID 36119498, 2022). "Inhibition of CCT2, using doxycycline (doxy) inducible system to express CCT2 small hairpin RNAs (shRNA), in a syngeneic TNBC mouse model prevented tumor growth and impaired spheroid formation." (PMID 36185250, 2022). "The mRNA expression levels of TCP1, CCT2/3/4/5/6A/7/8 in HCC patients were lower in grade 1/2 than grade 3/4, while CCT6B expression decreased as the tumor grade increased." (PMID 34676169, 2021).
tumor (continued). "The Basal subtype showed the highest number of specific upregulated genes (DNAJC2, DNAJC6, HSPA5, HSPA14 and CRYAA), DNAJA3 and CCT2 were upregulated in Luminal B, and DNAJB3 was only upregulated in HER2 tumours." (PMID 29954368, 2018). "To demonstrate a correlation between STAT3 and the levels of CCT2 in tumors from SCLC patients, we used TMAs containing SCLC tumor cores for analysis of both CCT2 and STAT3." (PMID 29299146, 2017). "CCT2 expression in BRCA and THYM was significantly different from tumor stage." (PMID 36119498, 2022). "In summary, our results indicated that subunits of TRiC displayed varying degrees of abnormal expressions, and CCT2, CCT3, CCT5, CCT6A, CCT7, and CCT8 were significantly upregulated in BCa patients and their upregulation was positively correlated with BCa tumor stage." (PMID 33815471, 2021). "Our work revealed that CCT2 tends to be overexpressed in tumor tissues compared with normal tissues." (PMID 33869000, 2021). "In this study, we determined the expression levels of CCT2 and PDIA3 by immunohistochemistry staining in tumor samples from 46 SC/ASC and 80 AC patients, and then investigated the relationship between these expression levels and tumor progression as well as the prognosis." (PMID 23782473, 2013). "In this study, we analyzed the expression of CCT2 and PDIA3 by IHC staining in 46 SC/ASC samples as well as in 80 AC samples, and found that both CCT2 expression and PDIA3 expression were significantly correlated with tumor progression and shorter survival time for patients with SC/ASC and AC." (PMID 23782473, 2013).
infection (5 papers, 2010 to 2024). The state of being infected such as from the introduction of a foreign agent such as serum, vaccine, antigenic substance or organism. "cct-2 and daf-19 RNAi worms were more susceptible to infection, suggesting that these genes are induced as a protective mechanism by C. elegans." (PMID 25187942, 2014). "We infected S2 cells with FHV after RNAi-mediated suppression of Cct1, Cct2, or both genes, and measured viral RNA and protein accumulation at 12 h after infection." (PMID 20236518, 2010). "In addition, the interference of human ATP5F1B (HGNC:830) and CCT2 (HGNC:1615) mRNA by siRNA decreases the productive infection of HeLa P4/R5 cells of HIV-1 HXB2." (PMID 36333693, 2022). "At every 6 h after infection with ZIKVCam, we harvested samples for testing protein expression and found that the expression levels of viral proteins and RNA were suppressed or delayed in CCT2-KD cells compared with control cells." (PMID 32397176, 2020). "Four of the identified genes, aco-1, cct-2, daf-19 and hsp-60, were knocked down using RNAi and ACO-1, CCT-2 and DAF-19, which were identified as up-regulated in response to S. flexneri infection, were found to be involved in the infection process." (PMID 25187942, 2014).
neurodegenerative disease (4 papers, 2022 to 2025). A disorder of the central nervous system characterized by gradual and progressive loss of neural tissue and neurologic function. "Meanwhile, pathway enrichment analysis showed that CCT2 is associated with multiple neurodegenerative diseases in animals, which is consistent with previous findings." (PMID 40374738, 2025). "The novel ubiquitin-binding receptor, CCT2, promotes autophagic clearance of various toxic protein aggregates associated with neurodegenerative diseases (Zhang and Klionsky., 2022)." (PMID 36704351, 2022). "The selectivity of CCT2-mediated aggrephagy for solid aggregates has implications for neurodegenerative diseases." (PMID 39478698, 2024). "In fact, a recent study found a decrease in CCT2 levels during the aging process and in multiple neurodegenerative diseases." (PMID 35988155, 2022). "Furthermore, CCT2 may contribute to neurodegenerative diseases and metabolic dysregulation through its involvement in mitochondrial function and protein homeostasis, highlighting its potential importance in retinal health and disease." (PMID 40374738, 2025). "The ability of CCT2 to specifically target solid aggregates suggests that it may play a unique role in diseases characterized by the accumulation of insoluble protein aggregates, such as neurodegenerative diseases." (PMID 39478698, 2024).
psychiatric diseases (1 paper, 2024). "So far, there is no relevant research on CCT2, EPRS, and PRPF8 in psychiatric diseases." (PMID 38664915, 2024).
CCT2 also shares sentences with these, for which no sentence is quoted: non-small cell lung carcinoma (3 papers); adenocarcinoma (2); adenosquamous carcinoma (2); colon adenocarcinoma (2); Lung squamous cell carcinoma (2); adenylosuccinate lyase deficiency (1); amyotrophic lateral sclerosis (1); arrhythmogenic right ventricular dysplasia 5 (1); astrocytoma (1); Bardet-Biedl syndrome (1); benign tumors (1); bladder urothelial carcinoma (1); blastoma (1); brain tumor (1); carcinoid (1); Charcot-Marie-Tooth disease (1); choroid plexus carcinoma (1); Clear cell sarcoma of the kidney (1); colon inflammation (1); colonic carcinoma (1); conduct disorder (1); diabetic nephropathy (1); diffuse intrinsic pontine glioma (1); endometrial carcinoma (1); Esophageal carcinoma (1); gallbladder adenocarcinoma (1); gallstones (1); ganglioneuroblastoma (1); hemangioblastoma (1); Huntington disease (1).
A further 23 diseases each share a sentence with CCT2 in 1 paper.